IGFBP3 (insulin like growth factor binding protein 3)
Diseases named in the same sentence as IGFBP3 in open-access papers (continued):
Sharing a sentence is not in itself a finding about the gene and the disease.
tumor (continued). "Consequently, the expression of CA9, NDUFA4L2, EGLN3, BHLHE41, VWF, IGFBP3, and ANGPTL4 is associated with ccRCC tumor progression and decreases at stage 4 after initial growth relative to normal tissues." (PMID 34046336, 2021). "Furthermore, IGFBP3 is decreased in HCC, and low expressions of IGFBP3 are remarkably linked to the tumor size, portal vein invasion, and histological differentiation, as well as capsular invasion." (PMID 34692847, 2021). "IGFBP3 was observed in vesicles, the neoplasm and cytosol in the Human Protein Atlas (HPA)." (PMID 34512163, 2021). "Similarly, compared with the xenograft tumours from mice injected with the saline solution, the tumour tissues from the CVB-treated mice presented substantially decreased numbers of IGFBP3-, Snail-, Vimentin- and Ki-67-positive cells." (PMID 34512163, 2021). "In addition, the GEPIA database showed that IGFBP3 was overexpressed in several malignant tumours, and the highest level was observed in ccRCC." (PMID 34512163, 2021). "Immunostaining of orthotopic tumor sections with an anti-NF-κB antibody showed similar levels of NF-κB-positive staining in irradiated IGFBP3-expressing tumor cells (n = 5; Immunoreactivity score (IRS): 8 per section) compared to controls (n = 5; IRS: 5.8 ± 1.02 per section)." (PMID 33712045, 2021). "HIF-1α could react with IGFBP3 associated with tumor arrest signals, while HIF-2α assists tumor growth and aggressiveness." (PMID 34824343, 2021). "IGFBP7, similar to IGFBP3, might have a dual role as a tumor suppressor within the IGF/insulin system while simultaneously having tumor-promoting effects through other pathways." (PMID 34606580, 2021). "Additionally, immunostaining for IL-6 demonstrated significant upregulation of IL-6 in irradiated IGFBP3-expressing tumor cells (n = 5; IRS: 4.6 ± 0.8718 per section) relative to controls (n = 5; IRS: 7.6 ± 0.4 per section; p = 0.0143)." (PMID 33712045, 2021). "IGFBP1 and IGFBP3 were recognized as tumor suppressor factors in GC." (PMID 33931579, 2021). "However, major gaps in our knowledge need fulfillment in future studies regarding the impact of Ang1 and/or IGFBP3 overexpression in cancer cells in the establishment of co-opted tumor lesions in the liver." (PMID 34376784, 2021). "IGFBP‐3 acts as a tumor suppressor gene in several human carcinoma cancers examined." (PMID 34485840, 2021). "IGF-1R knockdown via siRNA could upregulate the expression level of IGFBP-3 in tumor drug resistance cells and lead to promoting the sensitivity of LC cells to cisplatin and radiation." (PMID 33768092, 2021). "However, the tumors started to grow again after 15 d of tumor cell implantation (IGFBP3 was continuously stimulated for expression for 7 d)." (PMID 34824343, 2021). "IGFBP-3 has been shown to regulate tumor growth and angiogenesis by modulating IGF bioavailability." (PMID 33801272, 2021). "In murine xenografts, the inhibition of IGFBP3 increased tumor growth." (PMID 34046336, 2021). "Studies of other tumor types have provided some insight into the specific mechanisms of IGFBP3." (PMID 34745945, 2021). "We observed that the higher level of Ki-67 in IGFBP3-expressing tumors than that in control tumors 4 weeks after IR, indicating that the higher proliferation index of IGFBP3-expressing tumors might possibly lead to tumor regrowth at a later time point." (PMID 33712045, 2021). "In another study with SCCs, nuclear FAK was shown to downregulate the expression of insulin-like growth factor binding protein 3 (IGFBP3), a tumor suppressor, by promoting the interaction between the transcription factor RUNX1 and the transcriptional suppressor Sin3a17." (PMID 32514188, 2020).
tumor (continued). "Interestingly, IGFBP-3 and DNA-PKcs expression levels were found to be increased in the surviving tumour cells of most cases after preoperative chemoradiotherapy." (PMID 32093285, 2020). "Although IGFBP-3 may utilize multiple mechanisms for its anti-tumor actions, current findings suggest that the IGFBP-3/IGFBP-3R axis may constitute a novel anti-tumor/anti-metastatic signaling pathway and a novel potential therapeutic target in cancer." (PMID 32443727, 2020). "Further studies have shown that IGFBP-3 may exert pro-survival or proliferative effects, as well as pro-apoptotic effects, on tumor cells; additionally, studies have demonstrated that IGFBP-3 modulates overall tumor growth." (PMID 33180852, 2020). "Similarly, IGFBP3 was sARE-like in its upregulation by low-dose dox and potential anti-tumor effects." (PMID 32198885, 2020). "Taken together, these results indicated that cyclin G2 functioned as a tumor suppressor in OSCC through its interaction with IGFBP3 and the subsequent blockage of the connection between integrin and IGFBP3, the phosphorylation of FAK and the FAK-SRC-STAT signaling pathways." (PMID 33240810, 2020). "In addition, functional IGFBP-3 protein levels in circulation or in tumor and ratio of IGF-I and IGFBP-3 in circulation should be further factored to interpret the TCGA data." (PMID 32443727, 2020). "Meanwhile, other studies have indicated that tumour protein and mRNA levels of IGFBP-3 may be useful prognostic markers." (PMID 32093285, 2020). "Although tumour IGFBP-3 may contribute to tumour progression in OSCC, these discrepancies reflect the diversity of IGFBP-3 functions, including IGF-dependent and independent effects, in different types of cancers." (PMID 32093285, 2020). "Targeting the IGF1 and IGFBP3 signaling pathway may strengthen GO-related cytotoxicity with the potential to increase the survival of patients affected by this tumor." (PMID 32742448, 2020). "Other studies have reported that overexpression of IGFBP-3 is correlated with increased tumour size and lymph node metastasis in patients with OSCC, suggesting that IGFBP-3 may enhance malignancy in OSCC." (PMID 32093285, 2020). "IGF‐binding protein 3(IGFBP‐3)has previously been identified as tumor marker." (PMID 31218761, 2019). "Moreover, low expression of IGFBP3 correlated clinically with higher tumor grade, advanced stage, and poor survival." (PMID 31527696, 2019). "From our perspective, the opposite effect of IGFBP3 may be dependent on the different tumor origin and cell context and the overexpression of IGFBP3 in HNSCC implied that it may function as a tumor promoter." (PMID 31304688, 2019). "Therefore, both the subcellular localization and prognostic value of tumor IGFBP-3 staining appears to be highly dependent on tumor type." (PMID 29623068, 2018). "In both tumor models, tissue staining for IGFBP-3 was predominantly nuclear." (PMID 29623068, 2018). "In addition, some other HIF downstream targets, such as VEGF or Cyclin D1, are strongly pro-tumor growth, whereas other HIF downstream targets such as GLUT1 or IGFBP3, are obviously tumor suppressive." (PMID 30355451, 2018). "Taken together, our results suggest that B-Myb functions as a tumor-promoting gene via suppressing IGFBP3 and could serve as a novel therapeutic target in NSCLC." (PMID 29772705, 2018). "The first goal of this study was to evaluate tumor IGFBP-3 abundance for potential value as a prognostic indicator in basal-like triple-negative breast tumors, using as model systems, two basal-like TNBC cell lines grown as orthotopic xenograft tumors in nude mice." (PMID 29623068, 2018). "Since we found, using cell models, that IGFBP-3 downregulation attenuated the synergism between the EGFR and SphK inhibitors, we proposed that tumor IGFBP-3 levels might act as a biomarker for the efficacy of the combination therapy." (PMID 29623068, 2018).
tumor (continued). "However, results from IGFBP3−/− knockout mice shows an accelerated tumor growth as compared to the wild type mice, suggesting anti-oncogenic role of IGFBP3 in this specific experimental model." (PMID 28393842, 2017). "Similarly, the up-regulation of both anti-angiogenic factors, TIMP-4 and IGFBP3, suggests that NX treatment prevent tumor angiogenesis by controlling the secretome of U87-MG cells." (PMID 29156770, 2017). "With VEGF tumor overexpression, IGFBP-3, PTX-3, and TIMP-4 increased significantly in the plasma." (PMID 27995973, 2016). "In addition to being highly expressed in some tumors, IGFBP-3 expression has also been observed in tumor endothelial cells and stroma, possibly modulating overall tumor growth." (PMID 27448965, 2016). "We speculate that IGFBP-3 acts, at least in part, to protect against the potential growth-inhibitory effect of tumor T-cells, and may modulate the relationship between tumor vascularity and T-cell infiltration." (PMID 27448965, 2016). "Additionally, we observed up-regulated IGFBP3 protein in OSCC tissues as compared to the non-tumor epithelium using IHC." (PMID 26540630, 2015). "It was proposed that the IGFBP-3 gene could be a putative tumor suppressor gene and/or therapeutic target for human cancers." (PMID 26370590, 2015). "It is clear that IGFBP-3 functions as a tumor promoter in some cancers, including TNBC." (PMID 26221601, 2015). "Interestingly, we further observe that IGFBP-3 had favorable impact on the tumorigenicity of ESCC cells in nude mice by using an in vivo imaging system (IVIS) to monitor tumor growth treated with IR." (PMID 26670461, 2015). "Because adhesion of vascular endothelial cells (ECs) within the tumor microenvironment plays a fundamental role in tumor angiogenesis and progression, we examined the effect of IGFBP-3 on HUVEC adhesion to ECM using HUVECs that were infected with either Ad-EV or Ad-BP3." (PMID 25945837, 2015). "To further study the effects of IGFBP-3 on tumor growth and progression, we investigated whether IGFBP-3 can alter cancer cell adhesion to ECM." (PMID 25945837, 2015). "We observed that the tumor mass of treated mice was occupied by large necrotic areas that accounted for most of the tumor size, indicating that the cytotoxic effects of IGFBP-3 were more profound than those anticipated by the simple evaluation of in vivo tumor size (not shown)." (PMID 24905466, 2014). "Indeed, it is well known that IGFBP-3 has a biological activity of its own on a variety of tumor cell lines." (PMID 24905466, 2014). "A third question to be answered is how the tumor microenvironment may influence IGFBP3 expression, and how the effects of IGFBP3 in CAFs and epithelial cells cooperate." (PMID 25374561, 2014). "Secondly, tumour samples taken from patients were immuno-stained for both IGFBP-3 and MMP-9." (PMID 24905466, 2014). "However, the IGFBP-3-induced reversion of tumor cells towards a melanocytic phenotype observed in vitro was also apparent in vivo, since tumors from treated mice appeared darker and had higher tyrosinase activity." (PMID 24905466, 2014). "Concomitantly, the tumor growth was greatly impaired, suggesting that IGFBP3 might suppress tumor growth in an IGFIR-independent manner." (PMID 24260413, 2013). "Interestingly, suppression of IGFBP3 expression, instead of retarding tumor growth, very significantly enhanced the tumor growth." (PMID 24260413, 2013). "The IGFBP-3 protein can bind to cell surface glycosaminoglycans or via specific molecules such as low-density lipoprotein-related protein in modulating apoptosis and tumor suppression." (PMID 23592916, 2013). "IGFBP-3 has been known to function as a tumor suppressor or a cell cycle inhibitor in PC cells." (PMID 22879989, 2012). "Moreover, tumor cells lost their invasiveness when recombinant human IGFBP3 was added to the culture medium, as evidenced by the transwell assays with Matrigel coated inserts." (PMID 22401581, 2012).
tumor (continued). "Conversely, it has been postulated that the suppression of the putative tumor suppressor gene IGFBP3 could lead to elevated levels of insulin-like growth factors, thus promoting tumor growth." (PMID 22401581, 2012). "In addition, we reveal that IGFBP3 is epigenetically silenced in HB cell lines and that the reintroduction of IGFBP3 leads to the inhibition of tumor cell migration and invasion." (PMID 22401581, 2012). "The association is not substantially modified by IGFBP3, and does not differ markedly by menopausal status, but seems to be confined to oestrogen-receptor-positive tumours." (PMID 20472501, 2010). "However, since IGFBP-3 expression and IGFBP-3 promoter methylation were correlated with disease stages and tumor grades, the associations of these variables with survival rates was not independent of age, stage and grade." (PMID 20003326, 2009). "Because IGFBP3 regulates cell proliferation and survival and mediates the anti-tumor effects of a number of anti-cancer agents through both IGF-dependent and IGF-independent mechanisms, we hypothesized that IGFBP3 mediates GIST cell response to imatinib." (PMID 19903356, 2009). "Conventional studies mainly think that insulin-like growth factor-I (IGF-I) and IGF-binding protein-3 (IGFBP-3) may promote and inhibit tumor growth, respectively." (PMID 19549343, 2009). "Conventional studies coordinately think that IGF-I and IGFBP-3 may promote and inhibit tumor growth, respectively." (PMID 19549343, 2009). "These suggest that IGF-I may promote tumor cell growth, while IGFBP-3 acts as a tumor suppressor gene." (PMID 19549343, 2009). "In a previous study to determine how imatinib exerts its anti-tumor effects, we demonstrated that insulin-like growth factor binding protein-3 (IGFBP3) expression is up-regulated after imatinib treatment in the imatinib-responsive GIST cell line GIST882 as well as KIT-expressing tumor samples." (PMID 19903356, 2009). "In addition to measuring objective tumor response, a few studies have incorporated serum measurement of IGFBP-3 as a biomarker of disease progression." (PMID 19025658, 2008). "Median IGFBP-4 tumor expression was significantly greater in primary versus metastatic patients (70% versus 10%, p = 0.01) A trend for greater median IGFBP-3 sera concentration was observed in metastatic versus primary patients (4.9 μg/ml vs. 3.4 μg/ml, respectively, p = 0.09)." (PMID 19025658, 2008). "The expression level of IGFBP3 was higher in tumor tissues from BBDs than in those from cancer." (PMID 17210081, 2007). "Cancer tissues had significantly lower IGFBP3 expression than benign tumor tissues (p < 0.001)." (PMID 17210081, 2007). "Although there was a significant difference between the methylation levels of GSTP1 and IGFBP3 within tumour samples (P<0.0001; 95% CI=88.17, 174.22), the median RMS of both genes was significantly higher in tumours than in histologically normal adjacent prostate or BPH (P<0.0001)." (PMID 17453001, 2007). "Increasing levels of IGFBP-3 expression showed a trend with increased proliferation, oestrogen receptor (ER) negativity and HER-2 overexpression to suggest its association with poor prognostic tumours." (PMID 15642160, 2005). "Similarly, 94% (15 of 16) of HER-2-positive tumours expressed IGFBP-3 (1+/2+) versus 84% of HER-2-negative cancers (P = 0.065)." (PMID 15642160, 2005). "Our finding of an association between IGFBP-3 and HER-2 expression is preliminary and, although based on a limited number of HER-2-positive tumours, may suggest a role for HER-2 in IGFBP-3 growth modulation." (PMID 15642160, 2005). "The rise we measured may reflect increased proteolysis of IGFBP-3 that would make more IGF available to the tumour." (PMID 16052224, 2005). "While the growth suppression imported by IGFBP-3 suggests the potential for tumor suppression, polymorphisms, but no significant mutations were observed in a survey of several tumors." (PMID 15661074, 2005).
tumor (continued). "As a result, the expression of IGFBP-3 is suppressed in tumor cells." (PMID 15661074, 2005). "Fewer tumours expressed IGFBP-3 strongly (2+) and it was evident more frequently in DCIS." (PMID 15642160, 2005). "Poor prognostic tumours with increasing IGFBP-3 expression may relate to recent evidence in vitro in which the pro-apoptotic action of IGFBP-3 is reversed by the extracellular matrix protein fibronectin[B27,28]." (PMID 15642160, 2005). "Cigarette smoking was associated with significant exposure-related reductions (up to 13%) in mean serum IGFBP-3 levels in men (and to a lesser extent in women), an observation which may be relevant for smoking-related tumour development." (PMID 15354219, 2004). "Taken together, they found that ADAM28 is overexpressed in its activated form within human BC tissues by tumor cells and claim that ADAM28 is implicated in cell proliferation via increased bioavailability of IGF-I, which is released from the complex of IGF-I/IGFBP-3 by selective IGFBP-3 cleavage." (PMID 38317965, 2024). "As with breast cancer, IGFBP3 might contribute to the suppression tumor growth." (PMID 37373068, 2023). "Besides all these negative effects, there is also some evidence regarding a contrasting action of IGFBP3 which may be protective against tumor progression through an anti-proliferative and pro-apoptotic effect." (PMID 37373068, 2023). "However, IGFBP-3 primarily functions as a tumor suppressor, as supported by the findings that IGFBP-3 alterations at transcriptional and post-translational stages have implications in the pathogenesis of several malignancies, including breast, prostate, and lung cancers." (PMID 37253773, 2023). "Additionally, IGFBP3 depletion leads to the suppression of tumor growth." (PMID 35990326, 2022). "Thus, IGFBP-3 may act as either an oncogene or tumor suppressor depending on cellular context and tumor type." (PMID 35798794, 2022). "The anti-tumour effects of Rec8 are caused by downregulation of cell growth-related genes (G6PD, SLC2A1, NOL3, MCM2, SNAI1, and SNAI2) and also by upregulation of both apoptosis or migration inhibitors (Gadd45G and LDHA) and tumour inhibitors (PinX1, IGFBP3, and ETS2)." (PMID 36139540, 2022). "This study showed that re-expressing IGFBP3 could transiently suppress tumor growth." (PMID 34824343, 2021). "Also, knockdown of IGFBP3 delayed tumor growth in mouse subcutaneous xenograft models." (PMID 32414222, 2020). "Finally, circ-0046263 plays a tumor-promoting role in NPC to enhance malignant behavior through the miR-133a-5p/IGFBP3 axis, which could be a potential target for NPC therapy." (PMID 32703944, 2020). "Our study combined WGCNA with differential gene expression analysis, further verified by immune infiltration-type analysis and tumor stemness of microenvironment analysis, and we obtained the survival-related genes IGFBP3 and SOCS2, which may predict the prognosis of HCC." (PMID 33414813, 2020). "Insulin-like growth factor binding protein-3-dependent signaling may be viewed as a controversial target for cancer therapy, since in some cancers IGFBP3 appears to act as a tumor suppressor gene, but our data suggest the plausibility of this approach for women with TNBC." (PMID 29623068, 2018). "The reduced EO771 tumor growth observed in the knock-out mice relative to wild-type suggests that host-derived IGFBP-3 may facilitate tumor growth and/or survival, probably by an IGF-independent mechanism, since IGF-driven tumor growth is likely to be inhibited by IGFBP-3." (PMID 27448965, 2016).